RN7SL413P (RNA, 7SL, cytoplasmic 413, pseudogene)
Gene: Miscellaneous RNA gene on chromosome 13 (51,593,919 to 51,594,215, reverse strand). Ensembl gene ENSG00000242893.
Homologues: Orthologues: chimpanzee Metazoa_SRP (99% identical), macaque Metazoa_SRP (95% identical). Paralogues in human: RN7SL2 (82% identical), RN7SL1 (82% identical), RN7SL3 (82% identical), RN7SL321P (81% identical), RN7SL679P (80% identical), RN7SL126P (80% identical), RN7SL220P (80% identical), RN7SL566P (80% identical), RN7SL88P (80% identical), RN7SL218P (79% identical), RN7SL296P (79% identical), RN7SL426P (79% identical), and 699 more.